NFKBIA (NFKB inhibitor alpha)
Diseases named in the same sentence as NFKBIA in open-access papers (continued):
Sharing a sentence is not in itself a finding about the gene and the disease.
hip osteoarthritis (2 papers, 2018 to 2023). "NFKBIA was involved in the inflammatory effect of FLS, contributing to an elevated risk of hip osteoarthritis." (PMID 36681837, 2023).
Legionella infection (2 papers, 2023 to 2025). "Similar results were found for the NFKBIA gene, which was enriched in the influenza A, legionellosis, measles, and toxoplasmosis pathways; moreover, it was also upregulated in the M and L groups compared with the H group." (PMID 37759582, 2023). "The legionellosis pathway was characterized by the presence of four differentially expressed genes (DEGs), namely, HSPA1, NFKBIA, eEF1A, and GroEL." (PMID 37759582, 2023).
male infertility (2 papers, 2021 to 2024). The inability of the male to effect fertilization of an ovum after a specified period of unprotected intercourse. "Tao Wang discovered an association between the risk of idiopathic male infertility and two genetic polymorphisms of the NFKBIA gene in China." (PMID 39336733, 2024).
memory impairment (2 papers, 2025). "Specific targets, such as NFKBIA, Cxcl12 (C‐X‐C motif chemokine ligand 12) and Vav3, along with key signalling pathways like chemokine, Wnt and NF‐kappa B, may mediate the effects of exercise on METH‐induced learning and memory impairments." (PMID 40782057, 2025).
metastatic tumors (2 papers, 2019 to 2020). "Case OVA_003 presented three actionable genes, whereby mutated PIK3CA and amplifications in MYC were shared between primary HGSOC and metastatic tumours, but deletions in NFKBIA were specific to the primary tumour." (PMID 32099096, 2020). "Similarly, case OVA_047, also did not present any actionable genes shared between primary and metastatic tumour, or specific to the primary tumour or contralateral ovary metastasis, with only a single actionable deleted NFKBIA gene in its metastatic tumour." (PMID 32099096, 2020). "Case OVA_048 also presented with a single actionable deleted NFKBIA gene in its metastatic tumour, but also had a single actionable IGF1R amplification in its primary tumour, whereas no actionable genes were shared between the primary HGSOC and metastatic tumours." (PMID 32099096, 2020).
primary immunodeficiencies (2 papers, 2010 to 2018). "A mutation in the gene NFKBIA encoding the classical inhibitor IκB-α has been described in two patients with primary immunodeficiency." (PMID 21171993, 2010).
primary progressive MS (2 papers, 2016 to 2020). "In particular, they found one predisposing allele in an IKBL gene and a protective allele in the promoter of the IκB-α gene, NFKBIA, which was decreased in frequency in primary progressive MS." (PMID 27695399, 2016). "One study has reported a genetic variant in the promoter region of NFKBIA that appeared to be protective for primary progressive MS, but thus far, there have been no other reports of mutations in this gene in MS." (PMID 32781504, 2020).
steatosis (2 papers, 2021 to 2023). Increased lipid within the cytoplasm of cells. "NFKB inhibitor alpha (Nfkbia), a key gene in the NF-κB signaling pathway, was expressed in elevated levels in HepG2 cells during steatosis and inflammation." (PMID 36839306, 2023). "NFKBIA overexpression is related to steatosis development by induction of hepatocyte apoptosis and secretion of TNF-α and IL-1β by Kupffer cells." (PMID 33785040, 2021).
T-cell immunodeficiency (2 papers, 2014 to 2019). A broad classification of disorders that affect the cell-mediated aspect of the immune response. "Mutations in NFKBIA are associated with T-cell immunodeficiency." (PMID 31419223, 2019).
toxoplasmosis (2 papers, 2020 to 2023). A parasitic disease contracted by the ingestion or fetal transmission of toxoplasma gondii. "Similarly, in the toxoplasmosis pathway, the M and L groups exhibited upregulation of two genes (HSPA1 and NFKBIA), and one DEG (MAP3K7IP1) was found to be downregulated in the M tidal flat." (PMID 37759582, 2023).
angioimmunoblastic T-cell lymphoma (1 paper, 2022). A mature T-cell non-Hodgkin lymphoma, characterized by systemic disease and a polymorphous infiltrate involving lymph nodes and extranodal sites. "In contrast, polyclonal T-cells had up-regulation of genes related to HTLV-1 infection (NFKBIA and EGR1), cytokine interaction (CCL4 and IL2RG), apoptosis, and inflammatory response, as well as genes down-regulated in angioimmunoblastic T-cell lymphoma (AILT)." (PMID 35464471, 2022).
autoimmune thyroid disease (1 paper, 2009). Inflammatory disease of the thyroid gland due to autoimmune responses leading to lymphocytic infiltration of the gland. "Distribution of IKBL and NFKBIA genotypes was compared in subgroups of GD patients stratified by clinical parameters, including gender, age of GD onset, presence of clinically evident ophthalmopathy, family history of autoimmune thyroid diseases and smoking habits." (PMID 19886988, 2009).
basal cell adenocarcinoma (1 paper, 2021). "Another study found CTNNB1 mutations in basal cell adenomas and, among other alterations, focal CYLD deletion and biallelic inactivation of NFKBIA in a case of basal cell adenocarcinoma." (PMID 32892208, 2021).
brain cancer (1 paper, 2017). A primary or metastatic malignant neoplasm affecting the brain. "In brain cancer models, mostly two distinct mechanisms initiate NF-κB signaling: one is EGFR signaling and another, the deletion of the NFKBIA gene that encodes IκBα." (PMID 28346397, 2017).
breast invasive carcinoma (1 paper, 2024). "The analysis of the clinical stages of patients with breast invasive carcinoma indicated that the BAX, BCL2L1, CASP8, CASP9, RELA, and NFKBIA gene expression levels were higher in stages 3 and 4 for all BRCA patients, and in stage 4 for BRCA-LumA patients, than in other clinical stages." (PMID 38542508, 2024).
Candida infection (1 paper, 2019). "NFKBIA gene expression was observed 12 h after Candida infection." (PMID 31413153, 2019).
cardia cancer (1 paper, 2021). A malignant neoplasm involving the cardia of stomach. "They found that the NFKBIA rs696 site was linked with the susceptibility of cardia cancer while NFKBIA rs2233406 mutation was associated with the susceptibility of non-cardia cancer, with heterozygous mutations increasing the risk of non-cardia cancer." (PMID 34440074, 2021).
chorioamnionitis (1 paper, 2019). A morphologic finding indicating inflammation of the fetal sac membranes. "Incidentally, NFKBIA appears to be upregulated in placenta with history of chorioamnionitis, as well as those complicated by preterm premature rupture of membrane (PPROM) cases." (PMID 30744680, 2019).
diabetic foot ulceration (1 paper, 2023). "Besides, NFKBIA affects the wound healing in diabetic foot ulceration (DFU) (p=0.006), MYC and SCD are related to pyroptosis and immune infiltration in T2DM (p=0.001)." (PMID 37293508, 2023).
empyema (1 paper, 2010). An accumulation of pus in a body cavity, usually the pleural space. "Common genetic variants in the immune response genes PTPN22 and NFKBIA have previously been identified in association with empyema susceptibility, although additional genes are likely to be involved." (PMID 20078874, 2010).
epididymitis (1 paper, 2021). Inflammation of the epididymis. "As an inflammatory mediator, the content of NFKBIA may decrease, while cytokines such as IL6 may increase in the epididymitis." (PMID 34153045, 2021).
esophageal tumours (1 paper, 2013). "In line with this, NFKBIA -826 CT+TT and 3’UTR AG+GG genotypes seem to be associated with lower risk of upper and lower third esophageal tumour respectively." (PMID 24324738, 2013).
Graves disease (1 paper, 2009). Graves' disease is an autoimmune disorder that leads to overactivity of the thyroid gland (hyperthyroidism).It is caused by an abnormal immune system response that causes the thyroid gland to produce too much thyroid hormones. "The aim of this study was to investigate an association of polymorphisms in two genes encoding NF-κB inhibitors: IKBL (encoding inhibitor of κB-like) and NFKBIA (encoding κB inhibitor α), withsusceptibility to and phenotype of Graves' disease (GD)." (PMID 19886988, 2009). "The present study investigated a role of selected polymorphisms within genes encoding IκB: IKBL (encoding IκBL) and NFKBIA (encoding IκBα) in development of Grave's disease (GD) in the Polish population." (PMID 19886988, 2009). "Frequencies of NFKBIA promoter haplotypes in subgroups of patients with Graves' disease stratified by clinical activity of thyroid associated ophtalmopathy assessed according to the NOSPECS classification." (PMID 19886988, 2009). "Distribution of IKBL and NFKBIA genotypes in subgroups of patients with Graves' disease stratified by clinical activity of thyroid associated ophtalmopathy assessed according to the OSPECS classification." (PMID 19886988, 2009).
hearing loss (1 paper, 2023). "We performed a genome-wide association study (GWAS) in 777 NPC patients and identified rs1050851 (within the exon 2 of NFKBIA), a variant with a high deleteriousness score, to be significantly associated with hearing loss risk (HR = 5.46, 95% CI 2.93–10.18, P = 9.51 × 10–08)." (PMID 37062025, 2023).
hypertensive heart disease (1 paper, 2021). Abnormal enlargement of the heart resulting from long-standing hypertension. "The findings of the PPI network indicated that IL-6, TNF, IL-1β, and NFKBIA were predicted as the main genes of AS-IV against hypertensive heart disease and the KEGG pathways analysis showed that TNF signaling pathway was its key pathway." (PMID 34803698, 2021).
measles (1 paper, 2023). A highly contagious viral infection caused by the measles virus. "Regarding the measles pathway, the M group showed significant upregulation of three genes (HSPA1, NFKBIA, and EIF2S1), while the L group displayed upregulation of two genes (HSPA1 and NFKBIA)." (PMID 37759582, 2023).
pericarditis (1 paper, 2024). An inflammatory process affecting the pericardium. "Eleven variants were located in genes already associated with recurrent pericarditis (NLRP3, TNFRSF1A and MEFV) and five in inflammation/immunodeficiency-related genes (IFIH1, NFKBIA, JAK1, NOD2 and ALPK1)." (PMID 39347728, 2024).
respiratory failure (1 paper, 2023). The significant impairment of gas exchange within the lungs resulting in hypoxia, hypercarbia, or both, to the extent that organ tissue perfusion is severely compromised. "IL-R1 (rs3917267) and IL-10 (rs3024509) variants were related with respiratory failure (OR = 3.31, p = 0.001 and OR = 0.18, p = 0.003, respectively) as well as several haplotype combinations in NFKBIA, NFKBIZ, IL-R1 and IL-10 (p = 0,02, p = 0,01, p = 0,001, p = 0,03, respectively)." (PMID 38143267, 2023). "In our study, the haplotype combination of the polymorphisms in different NF-κB inhibitors genes (NFKBIA,NFKBIE and NFKBIZ) have been associated with respiratory failure, time to clinical stability and higher punctuations in the CURB-65 score." (PMID 38143267, 2023).
rhinitis (1 paper, 2024). An inflammation of the mucous membrane lining the nose, usually associated with nasal discharge. "At present, there is a lack of reports on the role of NFKBIA in rhinitis." (PMID 38469312, 2024).
RSV bronchiolitis (1 paper, 2025). "Polymorphic variants in the NFKBIA promoter are linked to an increased risk of hospitalization in severe RSV bronchiolitis and pulmonary hyperresponsiveness among children with respiratory viral infections identified within the first 12 months of life." (PMID 41516283, 2025).
SARS-CoV infection (1 paper, 2013). "Similarly, DUSP8, IL6, CXCL10, and NFKBIA are up-regulated in SARS patients, while PTX3 and CXCL2 have been shown to be involved in SARS-CoV infection." (PMID 23935999, 2013).
serous ovarian cancer (1 paper, 2010). "That is, one group including: SSBP1, IFI6 DDT, IFI27, C11orf92, NFKBIA, TNXB, NEAT1 and TFG, was up-regulated in most patients with stage III serous ovarian cancer." (PMID 20969748, 2010).
small cell lung carcinoma (1 paper, 2023). Small cell lung cancer (SCLC) is a highly aggressive malignant neoplasm, accounting for 10-15% of lung cancer cases, characterized byrapid growth, and early metastasis. "Consistently, our results of KEGG analysis also showed that the circRNA-related target genes, such as HIF1A and NFKBIA, were mainly associated with two signaling pathways: HIF-1 signaling pathway and small cell lung cancer." (PMID 37674577, 2023).
thymic carcinoma (1 paper, 2023). Thymic carcinoma (TC) is a type of thymic epithelial neoplasm characterized by a high malignant potential.
uterine disease (1 paper, 2022). "The dysregulation of iNOS and/or TLR signaling pathways in the endometrium mediated by NFKBIA could be contributing to the subfertility observed in cows after uterine disease." (PMID 35358206, 2022).
uveitis (1 paper, 2025). An inflammatory process affecting a part of or the entire uvea. "This study identified six significantly upregulated genes (CDKN1A, VCAM1, NFKBIA, ICAM1, IRF1, and CXCL10) and demonstrated that QHRGF exerts therapeutic effects on uveitis using in vivo experiments." (PMID 40718791, 2025).
tumor (305 papers, 2003 to 2026). "When the two mutation types of deletion (DEL) or AMP were counted separately, the gene NFKBIA was the only one found to be significantly amplified in the primary tumor showing significant mutation difference between the relapse and not‐relapse groups." (PMID 38733174, 2024). "Correspondingly, when NFKBIA expression was restored in NFKBIA‐deficient tumour cells, the malignant phenotype was weakened and chemosensitivity was increased." (PMID 37775993, 2023). "NFKBIA deletions and reduced IκBα levels are significantly associated to unfavorable outcomes and tumor recurrence in patients." (PMID 34572464, 2021). "Deletion and low expression of NFKBIA were associated with enhanced tumor aggressiveness and poor prognosis in LGGs." (PMID 27052952, 2016). "Mutations in NFKBIA have been described in multiple cancers including GBM cell lines suggesting its function as a tumor suppressor." (PMID 24889866, 2014). "A third line of evidence was provided by array-CGH tested on one primary tumor, where NFKBIA deletion, detected by CNV assay, was associated to the entire loss of chromosome 14." (PMID 24330732, 2013). "BT314 showed NFKBIA deletion in the primary tumor: this was confirmed by array-CGH, showing complete loss of the long arm of chromosome 14." (PMID 24330732, 2013). "GADD45A, a potent inhibitor of the c-Jun N-terminal kinase (JNK) cascade and NFKBIA, inhibits transcription factors associated with tumor growth and was up-regulated by doxorubicin in 12 probes." (PMID 18959781, 2008). "The identification of NFKBIA gene mutations, combined with studies showing an increased occurrence of certain single-nucleotide polymorphisms and haplotypes in different types of cancers, strongly suggests that NFKBIA acts as a tumor suppressor gene." (PMID 38469312, 2024). "Moreover, it was demonstrated that both NFKBIA deletion and reduced levels of IκBα are associated with tumor aggressiveness and poor prognosis." (PMID 34572464, 2021). "Thus, the present findings demonstrate that deletion and low expression of NFKBIA are associated with enhanced tumor aggressiveness and poor prognosis in LGGs." (PMID 27052952, 2016). "NFKBIA is a negative regulator of NFkB signalling, and its inactivation in various haematological and solid malignancies suggests a tumour suppressor role." (PMID 40289262, 2025). "NFKBIA has been identified as an inhibitor of nuclear factor-kappa B (NF-κB) and exerts an anti-tumor effect on GBM." (PMID 40661076, 2025). "The results show that BAX and BCL2L1 were significantly (p < 0.001) higher in the tumor tissue than in the normal tissue when comparisons were made, whereas NFKBIA was significantly (p < 0.001) higher in the normal than in the cancer tissue." (PMID 38542508, 2024). "The first evidence directly linking NFKB to tumor suppression was found in the epidermis overexpressing the NFKB inhibitory protein NFKBIA." (PMID 31363162, 2019). "Based on their functions, the literature and their occurrence within the candidate deleted FMCR, we propose RASSF3, IFNAR1, IFNAR2 and NFKBIA as novel candidate CRC tumour suppressor genes." (PMID 24367615, 2013). "Additionally, independent studies have identified loss-of-function mutations in NF-κB negative regulators, including NFKBIA, in NPC tumours." (PMID 40997749, 2025). "The expression level of NFKBIA was considerably higher in normal tissue than in tumors, suggesting that it may act as a tumor suppressor." (PMID 38542508, 2024).